EGR1 (early growth response 1)
Diseases named in the same sentence as EGR1 in open-access papers (continued):
Sharing a sentence is not in itself a finding about the gene and the disease.
lung carcinoma (continued). "Moreover, the EGR1 protein content was also reduced in different lung cancer cells contrasted with normal cells." (PMID 34497759, 2021). "Egr1 exerts a promoting effect on cancer metastasis in Oct4-overexpressing lung cancer." (PMID 31399076, 2019). "In lung cancer cells, Oct4 transactivated the Egr1 promoter and upregulated Egr1 expression." (PMID 31399076, 2019). "We next investigated whether Egr1 was involved in the enhancing effect of Oct4 on the metastatic potential of lung cancer cells in vitro." (PMID 31399076, 2019). "In the present study, we further explored the biological effect of Egr1 in lung cancer cells." (PMID 31399076, 2019). "To examine whether Oct4 upregulated Egr1 expression by transactivating the Egr1 promoter, we used a luciferase reporter assay to detect the Egr1 promoter activity in lung cancer cells after lentivirus-mediated overexpression of Oct4." (PMID 31399076, 2019). "However, the role of Egr1 in the metastasis of lung cancer remains undetermined, especially in regard to stem cell-related pathways." (PMID 31399076, 2019). "We show that the Egr1/OPN axis is regulated in Oct4-expressing lung cancer." (PMID 31399076, 2019). "A direct influence of Egr-1 on VEFG has been recently demonstrated in lung cancer cells, either by binding to the proximal region of the VEGF promoter and activating the VEGF expression or by enhancing the hypoxia inducible factor 1alpha- (HIF-1alpha-) mediated VEGF expression." (PMID 24967343, 2014). "Our data suggest that RA-induced changes in the expression of RARβ2, CYP26A1, CRBP1, RGS16, DUSP6, and EGR1 may be necessary for the retinoid anticancer signal in neuroblastoma, breast and/or lung cancer cells." (PMID 16012519, 2005). "Besides, NT157 decreased expression of oncogenes BCL2, CCND1, MYB, and MYC and increased genes related to cellular stress and apoptosis, JUN, BBC3, CDKN1A, CDKN1B, FOS, and EGR1 (p < 0.05), favoring a tumor-suppressive cell signaling network in the context of lung cancer." (PMID 36224313, 2022). "Therefore, EGR1 could regulate its downstream signals and target genes, thus having a tumor-suppressive role in human lung cancer." (PMID 34497759, 2021). "Another study also noted increased expression of EGR1 and downregulation of cancer-related pathways, suggesting possible protective effects in comorbid COPD-lung cancer settings." (PMID 41555409, 2026). "Resveratrol has been found to bind to synthetic or natural promoters of early growth response 1 (Egr-1) and to enhance the expression of growth arrest and DNA damage-inducible (GADD45) in A549 lung cancer cells." (PMID 38904027, 2024). "Our results demonstrated that EGR1 is upregulated in response to knockdown of DUXAP8, inhibiting lung cancer growth." (PMID 34235076, 2021). "The expressions of EGR1 and EGR3 in 20 different types of human cancers were downregulated compared with that in normal tissues, including BRCA, lung cancer, and ovarian cancer." (PMID 34178038, 2021). "Egr1, osteopontin (OPN) and Oct4 expression in human lung cancer was determined by performing immunohistochemistry." (PMID 31399076, 2019). "In brief, we demonstrated that the transcription factor EGR1 is activated by TCM YYJD and such activation is involved in YYJD‐induced apoptosis in lung cancer cells." (PMID 31237749, 2019). "We detected Oct4, Egr1, and OPN expression in clinical specimens from 79 lung cancer patients, including 72 adenocarcinomas and 7 squamous cell carcinomas." (PMID 31399076, 2019). "The cofactors PRDM1, EGR1, and TOPORS were shown to be tumor suppressors in colon cancer, leukemia, and lung cancer, respectively." (PMID 28684851, 2017).
lung carcinoma (continued). "The previous evidence has confirmed the potential regulation role of TGFB on these genes, such as EGR1, EGFR, and IL6 in the lung cancer." (PMID 28959347, 2017). "Conversely, Egr-1, which is induced by ERK pathway activation, induces and enhances vascular endothelial growth factor-A (VEGF-A) in lung cancer." (PMID 25004251, 2014). "In contrast, EGR1, an oncogenic driver in prostate and lung cancers, did not change in our system, indicating a more PDAC-specific transcriptional program activated by platelet-derived defensins." (PMID 41303383, 2025). "For instance, EGR1, JUN, PPARG, and RELA may have a beneficial effect in lung cancer, related to inhibition of tumor proliferation and metastasis, induction of apoptosis, and sensitization for chemotherapeutic drugs." (PMID 36969247, 2023). "The data indicated that the CCNE1-high, CCNE1-high/EGR1-low, CCNE1-high/SCGB3A1-low and OTX1-high/CCNE1-high phenotypes, which might be involved in lung cancer malignancy, are related to poor prognosis in lung cancer." (PMID 36918558, 2023). "Egr1 is positively correlated with Oct4 and OPN in human lung cancer." (PMID 31399076, 2019). "Thus, these EGR1‐bound and YYJD‐responsive genes are potentially involved in biological activities we observed in YYJD‐treated lung cancer cells." (PMID 31237749, 2019). "Besides, the expression of EGR1 and miR-377-3p in fresh lung cancer tissues also showed a negative relevance." (PMID 34497759, 2021). "Thus, therapeutic strategies targeting the Oct4/Egr1/OPN axis may be further explored for the treatment of lung cancer, especially when lung cancer is refractory to conventional treatment due to cancer stem cells." (PMID 31399076, 2019). "However, the interaction between Egr1 and OPN in lung cancer remains largely unclear." (PMID 31399076, 2019). "We further delineate the EGR1 target genes in YYJD‐treated A549, including some apoptosis‐related genes such as KLF11,29, 30, 31 BCL2L1137, 38, 39, and DUSP6.40, 41 These observations suggest that the apoptosis of lung cancer cells induced by YYJD is possibly mediated by EGR1‐bound target genes." (PMID 31237749, 2019). "Study of mesothelioma and lung cancer cells has also suggested that the collagen receptor discoidin domain 1 (DDR1)-mediated upregulation of connective tissue growth factor (CTGF) and early growth response 1 (EGR1) upon IGF-I stimulation requires both IGF-IR and GPER." (PMID 31708873, 2019). "The retinoid 6-[3-(1-adamantyl)-4-hydroxyphenyl]-2-naphthalene carboxylic acid (AHPN), a cell proliferation inhibitor and apoptosis inducer has been shown to induce Egr-1 expression through ERK1/2 signaling pathway rather than activation of p38 in lung cancer cells." (PMID 25004251, 2014). "In lung cancer cell line A549, the upregulation of thrombospondin-1 (TSP-1), an anti-angiogenic and anti-invasion protein, upon cyclooxygenase (COX) inhibitors treatment is mediated by Egr-1, and Egr-1 directly binds and downregulates stathmin expression which regulates the dynamics of microtubules." (PMID 25004251, 2014). "Even though those genes were differentially expressed in A427 and M14 cells, further analyses revealed that EGR1 (but not several other genes we examined) displayed an expression pattern similar to that of MIG-6 across the four lung cancer cell lines and five melanoma lines." (PMID 22701735, 2012).
glioma (50 papers, 2009 to 2025). A benign or malignant brain and spinal cord tumor that arises from glial cells (astrocytes, oligodendrocytes, ependymal cells). "In glioma, EGR1 has been linked to the self-renewal of brain tumor-initiating cells, indicating an implication in the maintenance of niche populations." (PMID 34439267, 2021). "The network topology analysis performed in this study revealed a set of central nodes associated to glioma malignancy, such as Map3k14, Mapk1, Actn4, Hspa5, Atf2, Rac1,E2f1, Shc1, Pik3ca, Akt1, Vim and Egr1." (PMID 26582089, 2015). "In a 2007 study on rat C6 glioma cells, Egr1 expression was documented to be stimulated by the tricyclic antidepressant amitriptyline." (PMID 40862737, 2025). "Compared with those in normal control cells, the immunofluorescence signals of EGR1 and HOXB9 were obviously lower in glioma cells overexpressing miR‐192 (EGR1: 7.40 ± 0.79 vs. 28.35 ± 1.56; HOXB9: 10.75 ± 1.19 vs. 30.37 ± 2.28; *p < 0.05)." (PMID 40936205, 2025). "MiR‐192 was significantly reduced in glioma samples, and this factor downregulated EGR1 and HOXB9 via targeted binding, thus forming a semi‐open loop." (PMID 40936205, 2025). "Conversely, in gliomas and melanocytomas, EGR1 promotes tumor suppressor gene p21Waf1/Cip1 expression and induces apoptosis, functioning as a tumor suppressor in these cancers." (PMID 41155227, 2025). "In light of these findings, we illustrated a graphical abstract showcasing the regulatory role of GINS2 in TMZ chemosensitivity through the EGR1/ECT2 axis in glioma cells." (PMID 38467631, 2024). "In glioma, EGR1 induced the methyltransferase METTL3 to promote the proliferation and self-renewal of CSCs." (PMID 38467631, 2024). "Nonetheless, EGR1 upregulates tumor suppressor gene p21Waf1/Cip1 and leads to tumor cell apoptosis in gliomas and melanocytomas, and consequently, EGR1 serves as a tumor suppressor in these cancers." (PMID 33842351, 2021). "Poor expression of EGR1 increased the survival rate of patients with glioma, and EGR1 silencing suppressed proliferation but promoted cell cycle arrest of glioma cells." (PMID 34409922, 2021). "Similar to IL-6, EGR1 expression was reduced in glioma cells transfected with TMEM44-AS1, whereas overexpression of TMEM44-AS1 increases EGR1 expression." (PMID 34696771, 2021). "As expected, we found that knockdown of TMEM44-AS1 reduced the recruitment of EGR1 to the promoter of IL-6 in LN-18 and U251 glioma cells." (PMID 34696771, 2021). "Low EGR1 levels have also been reported to correlate with high cisplatin sensitivity in primary glioma cells." (PMID 32102425, 2020). "Recent studies have also shown that EGR1 silencing has antitumor effects in glioma and colorectal tumor models in vivo." (PMID 29719592, 2018). "The results confirmed that the basal level of high EGR1 expression will promote glioma proliferation and partly explained the reason why the patients with higher EGR1 expression showed shorter survival." (PMID 29246166, 2017). "Of interest, we found the expression level of EGR1 in glioma stem-like cells was sustaining higher than that in normal glioma cells." (PMID 29246166, 2017). "This was consistent with previous reports, which showed that EGF signaling increased the EGR1 mRNA concentration in human glioma cells within 30 min." (PMID 29246166, 2017). "Compared with the control group, Egr-1 expression was significantly higher in high-grade glioma tissue and C6 astroglioma cells." (PMID 28187447, 2017). "The results showed that the mRNA and protein expressions of Egr-1 in C6 glioma cells were also significantly higher than that in normal astrocytes (P < 0.01)." (PMID 28187447, 2017). "bFGF promotes GDNF expression accompanied with the activation of ERK5, ERK1/2 and their downstream transcription factors (c-fos, EGR1) in C6 glioma cells and results in C6 glioma cells proliferation." (PMID 29246166, 2017).
glioma (continued). "The results showed that mRNA and protein expression of Egr-1 in high-grade glioma tissue were significantly higher than that in normal brain tissue (P < 0.01)." (PMID 28187447, 2017). "Egr-1 expression was measured in high- and low-grade glioma and normal brain tissue, as well as rat C6 astroglioma cells and normal astrocytes." (PMID 28187447, 2017). "Expression of EGR-1 gene in glioma cells is induced by overexpression of EGFR and PDGFR genes, thus suggesting EGR-1 as a connection of growth factor stimulation with gene expression changes." (PMID 29138748, 2017). "Our results of xenografts further verified the inhibition of proliferation by stable knockdown EGR1 in glioma cells." (PMID 29246166, 2017). "Both mRNA and protein expression of Egr-1 were significantly increased (P < 0.01) after infection, indicating the successful establishment of a C6 glioma cell model with overexpressed Egr-1." (PMID 28187447, 2017). "In conclusion, our study clarified that stable knockdown EGR1 would inhibit glioma cell growth in vitro and in vivo." (PMID 29246166, 2017). "The expression of EGR1 is also decreased in human GBM compare to normal brain tissue, but the effect of EGR1 on glioma cell proliferation is still paradoxical." (PMID 29246166, 2017). "EGR1 expression levels in human gliomas are decreased compared with normal brain tissues, however, the patients with low EGR1 expression level showed significantly enhanced patient survival in all glioma patients." (PMID 29246166, 2017). "The effects of Egr-1 overexpression on these outcomes were elucidated using a C6 glioma cell model with decreased histone acetylation in GDNF promoter II following treatment with the histone acetyltransferase (HAT) inhibitor curcumin." (PMID 28187447, 2017). "EGF or PDGF can induce the synthesis of EGR1 via ERK signal pathway in human glioma cells, suggesting that EGR1 functions as a “third messenger” in glioma cells." (PMID 29246166, 2017). "EGR1 expression levels in 39 glioma tissues and 10 normal brain tissues were tested by RT-qPCR and Western-blotting." (PMID 29246166, 2017). "Meanwhile, EGR1 overexpression induced by EGF was able to promote the proliferation of glioma cells." (PMID 29246166, 2017). "Subsequently, the expression of Egr-1 in human high-grade and low-grade glioma tissues, normal brain tissue, and rat C6 astroglioma cells and normal astrocytes were measured by real-time polymerase chain reaction (PCR) and western blot." (PMID 28187447, 2017). "Nonetheless, EGR1 was down-regulated in glioma cells compared with normal brain tissue, its role on proliferation in glioma remains controversial." (PMID 29246166, 2017). "Although EGF can improve EGR1 expression and promote glioma cells proliferation, many articles proved that high EGR1 expression would inhibit cells growth." (PMID 29246166, 2017). "We showed here that the expression of EGR1 is reduced in human glioma tissues compare to normal brain tissues, which is consistent with the result of TCGA." (PMID 29246166, 2017). "Egr-1 expression was measured in high-grade and low-grade glioma tissues and normal brain tissue using real-time PCR and western blot." (PMID 28187447, 2017). "In contrast, EGR1-expressing cells were more frequent in high grade gliomas where the nuclear expression of EGR1 was restricted to proliferating/progenitor cells." (PMID 29246166, 2017). "But, stable knockdown of EGR1 in GSCs and normal glioma cells inhibited growth in cellular level and xenografted tumor." (PMID 29246166, 2017). "CPZ has also been shown to inhibit cell-cycle progression in rat glioma C6 cells by inducing p21Waf/Cip1/Egr1 expression and to induce autophagic cell death by inhibiting the AKT/mTOR pathway in human glioma U87-MG cells." (PMID 28455961, 2017). "Because of its paradoxical function in gliomas, further elucidation of its mechanism of EGR1 regulating the proliferation remains essential." (PMID 29246166, 2017).
glioma (continued). "Recently, a research indicate the hyperacetylation of H3K9 at EGR1 binding sites in promoter region II of the GDNF gene can up-regulate the binding of EGR1 to increase GDNF gene transcription in glioma cells." (PMID 26376677, 2015). "There is a Elk-1 binding site in Egr-1 promoter, and in C6 glioma cells, ERβ-activated Egr-1 transcription is through ERK/Elk-1 pathway." (PMID 25004251, 2014). "Our results provide new preliminary evidence for the role of EGR-1 as a molecular factor involved in the chemosensitivity of glioma." (PMID 21366897, 2011). "For these properties and for being deregulated in human gliomas, as in other tumors, we sought to look for correlations between the levels of EGR-1 expression in our cell lines and their sensitivity to genotoxic anticancer drugs." (PMID 21366897, 2011). "We concluded that the levels of EGR-1 protein in each cell line from wild-type cases of glioma strongly correlate with sensitivity to cisplatin." (PMID 21366897, 2011). "Our findings further corroborate other studies showing that an activation of MAPK signaling pathway in U-87MG glioma cells leads to a proliferation arrest mediated by an increase in EGR-1 expression which concomitantly stimulates p21 transcription." (PMID 21079728, 2010). "In human glioma cells, for example, we have shown that stimulation of the G-protein coupled neurokinin receptor-1 by substance P induces the biosynthesis of Egr-1 via the transactivation of the EGF receptor." (PMID 19432968, 2009). "Mechanistically, TMEM44-AS1 could transcriptionally regulate Myc and EGR1/IL-6 signaling in glioma cells." (PMID 34696771, 2021). "EGR1 protein expression was found in all 207 gliomas, but with considerable inter-tumour variation." (PMID 32518380, 2020). "EGR1 and EGR3 have been linked to glioblastoma stemness and tumour progression, and this study aimed to investigate their spatial expression and prognostic value in gliomas." (PMID 32518380, 2020). "Overall 207 gliomas including 190 glioblastomas were EGR1/EGR3 immunostained and quantified." (PMID 32518380, 2020). "EGR1 has also been shown to promote a glioma stem cell-like phenotype." (PMID 32867190, 2020). "Based on this, we hypothesized that EGR1 and EGR3 may be associated with tumour progression, possibly mediated through promotion of tumour cell migration, and thus hold prognostic value in gliomas." (PMID 32518380, 2020). "Since CCND1 is one of the molecules which regulate the process from the G1 phase into the S phase, we hypothesized that CCND1 may be regulated by EGR1 in glioma." (PMID 29246166, 2017). "This indicates that highly expressed Egr-1 may be involved in regulating the high-level transcription of GDNF in high-grade glioma cells." (PMID 28187447, 2017). "So, we hypothesized that growth of glioma stem-cell-like cells in vivo was relative to overexpression of EGR1." (PMID 29246166, 2017). "Did the EGR1 perform different effects on proliferation in glioma stem cells and glioma cell lines?" (PMID 29246166, 2017). "Moreover, Egr-1 overexpression has been shown to significantly promote the infiltration and migration of high-grade glioma cells, which is consistent with the biological effect induced by the high-level GDNF transcription." (PMID 28187447, 2017). "Our results show that stable knockdown EGR1 would inhibit glioma proliferation." (PMID 29246166, 2017). "Egr-1 expression was abnormally increased in C6 glioma cells." (PMID 28187447, 2017). "This is compatible with a hypothesis that CRY2 controls Egr1 gene expression and maybe key to glioma growth and development." (PMID 29100427, 2017). "Moreover, the growth factor EGF stimulated glioma cells proliferation partially by enhancing EGR1 expression." (PMID 29246166, 2017).